AKTIP (AKT interacting protein)
Description:
Component of the FTS/Hook/FHIP complex (FHF complex). The FHF complex may function to promote vesicle trafficking and/or fusion via the homotypic vesicular protein sorting complex (the HOPS complex). Regulates apoptosis by enhancing phosphorylation and activation of AKT1. Increases release of TNFSF6 via the AKT1/GSK3B/NFATC1 signaling cascade. FHF complex promotes the distribution of AP-4 complex to the perinuclear area of the cell.
Synonyms: FTS; FLJ13258; FT1
Tractability: Antibody: UniProt places it where antibodies can reach, with high confidence; its Gene Ontology location is reachable by antibodies, with high confidence. PROTAC: its protein half-life has been measured.
Gene: Protein-coding gene on chromosome 16 (53,490,502 to 53,504,411, reverse strand). Ensembl gene ENSG00000166971.
Subcellular location: Cytoplasm; Cell membrane
Subcellular location (Human Protein Atlas): Basal body; Golgi apparatus; Nucleoli; Cytosol; Plasma membrane
Gene Ontology:
Molecular function: protein binding; ubiquitin conjugating enzyme activity; ubiquitin-like protein transferase activity
Biological process: early endosome to late endosome transport; endosome organization; endosome to lysosome transport; lysosome organization; positive regulation of protein binding; positive regulation of protein phosphorylation; protein localization to perinuclear region of cytoplasm; protein K63-linked ubiquitination; protein transport along microtubule
Cellular component: cytosol; FHF complex; HOPS complex; plasma membrane; cytoplasm
Genetic constraint (gnomAD): Loss-of-function variants: 16 observed, 39.69 expected, observed/expected ratio (o/e) 0.4, 90% interval 0.27 to 0.61. The synonymous counts are far from expectation, so gnomAD's model fits this gene poorly and the ratio says little. Missense variants: 262 observed, 369.25 expected, observed/expected ratio (o/e) 0.71, 90% interval 0.64 to 0.79. Synonymous variants: 93 observed, 125.8 expected, observed/expected ratio (o/e) 0.74, 90% interval 0.62 to 0.88.
Homologues: Orthologues: chimpanzee AKTIP (100% identical), macaque AKTIP (100% identical), rabbit AKTIP (98% identical), pig AKTIP (98% identical), dog AKTIP (97% identical), mouse Aktip (96% identical), rat Aktip (93% identical), tropical clawed frog aktip (83% identical), zebrafish aktip (78% identical), Drosophila melanogaster peo (29% identical), Caenorhabditis elegans ubc-19 (29% identical), Drosophila melanogaster CG16894 (24% identical). Paralogues in human: UBE2N (16% identical), UBE2I (16% identical), UBE2T (15% identical), UBE2O (15% identical), UBE2NL (15% identical), UBE2U (15% identical), UBE2Z (15% identical), UBE2C (14% identical), UBE2A (14% identical), UBE2B (14% identical), UBE2J1 (14% identical), UBE2G1 (13% identical), and 12 more.
Diseases named in the same sentence as AKTIP in open-access papers:
AKTIP is named in the same sentence as 28 diseases in open-access papers, as found by Europe PMC text mining. Sharing a sentence is not in itself a finding about the gene and the disease. The quoted sentences say what the papers report.
lymphoma (2 papers, 2018 to 2022). A malignant (clonal) proliferation of B- lymphocytes or T- lymphocytes which involves the lymph nodes, bone marrow and/or extranodal sites.
renal carcinoma (2 papers, 2022). A carcinoma arising from the epithelium of the renal parenchyma or the renal pelvis. "The human protein atlas data shows that two out of three genes, i.e., NKIRAS2 (unfavorable) and AKTIP (favorable), are prognostic marker in renal cancer." (PMID 35039759, 2022).
bladder cancer (1 paper, 2022). "The expression of the 3 genes in urothelial cancer ranges from moderate for NKIRAS2 (NCBI), variable for AKTIP (HPA), and variable for HLA-DQA1 as determined by an immune transcriptome analysis in bladder cancer." (PMID 35039759, 2022).
breast carcinoma (1 paper, 2022). "We herein report that AKTIP positioning at the rim is altered in the breast cancer cell line MCF7 and not in HeLa and A549." (PMID 36096808, 2022).
Insulin resistance (1 paper, 2021). Increased resistance towards insulin, that is, diminished effectiveness of insulin in reducing blood glucose levels. "For example, exosomal miR-20b-5p can target AKT-interacting protein (AKTIP), thereby affecting AKT activity and reducing glycogen accumulation in primary human skeletal muscle, leading to insulin resistance." (PMID 33714195, 2021).
uremia (1 paper, 2013). A clinical syndrome associated with the retention of renal waste products or uremic toxins in the blood. "AKTIP was lower in uremia, consistent with the proposals that insulin resistance may promote muscle wasting by inhibition of PI3K/Akt leading to activation of caspase 3 and the ubiquitin-proteasome proteolytic." (PMID 23809614, 2013).
urothelial carcinoma (1 paper, 2022). A malignant neoplasm derived from the transitional epithelium of the urinary tract (urinary bladder, ureter, urethra, or renal pelvis). "To test the prediction power of those genes, we developed a regression model for urothelial carcinoma that defined a set of 3 genes: NKIRAS2, AKTIP, and HLA-DQA1, which provides the likelihood of development of primary urothelial carcinoma with same estimation for male and female." (PMID 35039759, 2022).
cancer (8 papers, 2015 to 2025). A tumor composed of atypical neoplastic, often pleomorphic cells that invade other tissues. "In vivo, the reduction of the mouse counterpart of AKTIP, Ft1, induces premature aging of skin and bone and cancer predisposition." (PMID 37960940, 2023). "We also show that AKTIP alteration is observable in a HeLa-progerin model system, in which we combined the presence of a defined lamin mutation with a cancer cell setting." (PMID 36096808, 2022). "In future work, it will be interesting to investigate the association of AKTIP with cancer, because in tumorigenesis cell division is altered and since an implication in cancer has been described for TSG101 and other ESCRT factors." (PMID 34449766, 2021). "In future work, it will be interesting to explore if the AKTIP association with the ESCRT machinery has an impact on cancer, which has been indicated for TSG101 and more recently reported for the ESCRT III subunit CHMP4C." (PMID 34449766, 2021). "AKTIP is a protein enriched at the nuclear rim associated with cancer." (PMID 36096808, 2022). "This information taken together, suggest that AKTIP delocalization linked to lamin alterations could be further investigated as a mechanistic path to cancer disease." (PMID 36096808, 2022). "Here, we asked whether the distribution of AKTIP is altered in cancer cells and whether this is associated with alterations of lamins." (PMID 36096808, 2022). "In this study, we analyzed the positioning of AKTIP with super resolution and asked whether the distribution of AKTIP was altered in cancer cells and whether this was associated with alterations of lamins and/or with nuclear morphology." (PMID 36096808, 2022). "AKTIP is a factor associated with cancer at multiple levels." (PMID 36096808, 2022). "The data suggest that for predicting a potential implication of AKTIP in cancer cells, lamin alterations should be monitored in parallel with nuclear morphology." (PMID 36096808, 2022). "To this goal, we performed high resolution analyses of AKTIP in a set of cancer cell lines and in HGPS and EDMD lamin mutant cells." (PMID 36096808, 2022). "It is essential for cell survival, it is required to ensure the integrity of telomeres and genome, and, in vivo, the depletion of the mouse counterpart of AKTIP contributes to cancer aggressiveness." (PMID 36096808, 2022). "In conclusion, this work, on one hand, contributes to defining the relationship between AKTIP, lamin, and nuclear alterations in cancer cells." (PMID 36096808, 2022). "No substantial growth defects were observed in immortalized MEFs or human cancer lines treated with Ft1/AKTIP-interfering lentivectors." (PMID 26110528, 2015). "As a first step to analyze AKTIP localization, we imaged with high resolution HeLa cancer cells." (PMID 36096808, 2022). "In our previous work, we have shown that a protein named AKTIP (in humans, Peo in Drosophila) is organized in foci enriched at the nuclear rim in interphase cells and that a reduction in AKTIP (or Peo) results in telomeric defects, aging and cancer aggressiveness." (PMID 34449766, 2021). "Given that AKTIP is required for correct telomere function and genome integrity, its aberrant distribution in both cancer and laminopathic cells could be considered not only as a potential tool in disease prognosis, but also as a putative co-driver of the disease phenotypes." (PMID 36096808, 2022).
tumor (5 papers, 2018 to 2023). "We also report that it is the combined alteration of lamin and nuclear morphology that influences the localization of the tumor-associated factor AKTIP." (PMID 36096808, 2022). "We also found that the expression of lnc-AKTIP was significantly associated with the tumor staging of SNIP, which provided a new clue to clarify the epigenetic mechanism of SNIP." (PMID 35186045, 2022). "Performing the quantification of lamin expression and of nuclear morphology we observe that it is their combined alteration that influences the localization of the tumor-associated factor AKTIP." (PMID 36096808, 2022). "AKTIP has similarity with the tumor susceptibility gene TSG101." (PMID 36096808, 2022). "AKTIP and Ft1 have sequence similarity with TSG101, a tumor susceptibility gene that functions in viral budding and cytokinesis." (PMID 37960940, 2023). "AKTIP is implicated in essential cellular processes including telomere metabolism and cell division, and it is possible that the mislocalization of AKTIP in MCF7 alters its function possibly contributing to the tumor phenotype." (PMID 36096808, 2022). "Taken together these experiments show that when aberrant HGPS lamin is expressed in tumor cells it can induce alteration of nuclear morphology and a robust mislocalization of AKTIP." (PMID 36096808, 2022). "AKTIP has sequence similarity with the protein TSG101, a tumor susceptibility gene that functions as ESCRT I in viral budding and cytokinesis, and AKTIP acts in association with ESCRTs in cytokinesis." (PMID 35681444, 2022). "We further demonstrated the potential interaction between lnc-AKTIP and multiple tumor-related transcription factors and the significant correlation between the downregulation of lnc-AKTIP and the SNIP tumor stage." (PMID 35186045, 2022). "Lnc-AKTIP was revealed to be significantly related to the tumor stage (p = 0.007)." (PMID 35186045, 2022). "Considering the involvement of AKTIP in several essential cellular processes, we next evaluated whether there was a correlation between the localization of AKTIP at the nuclear rim and the proliferation rate of the tumor cell lines." (PMID 36096808, 2022). "Finally, AKTIP has sequence similarities with the protein TSG101, a tumor susceptibility gene." (PMID 36096808, 2022). "To explore the interrelation between AKTIP mislocalization, lamin expression, and nuclear morphology, we quantified these traits in all cell models, including tumor and non-transformed laminopathic cells." (PMID 36096808, 2022). "The results also point to the fact that lamin alterations per se are not predictive of AKTIP mislocalization, in both non-transformed and tumor cells." (PMID 36096808, 2022).
infection (2 papers, 2015 to 2016). The state of being infected such as from the introduction of a foreign agent such as serum, vaccine, antigenic substance or organism. "Western blotting performed on extracts from both cell types collected at 7 days post-infection showed that AKTIP depletion results in a substantial decrease in lamin A compared with control cells, without affecting lamin C and lamin B1 levels." (PMID 27512140, 2016).
AKTIP also shares sentences with these, for which no sentence is quoted: cervical cancer (4 papers); progeroid syndrome (4); bladder tumors (1); breast tumor (1); cardiac disease (1); cardiac hypertrophy (1); cardiomyopathy (1); Cognitive impairment (1); heart failure (1); Hepatitis (1); laminopathies (1); lipodystrophy (1); malaria (1); nephritis (1); peritonitis (1); pneumonia (1); prostate carcinoma (1); schizophrenia (1).